ORC6 (origin recognition complex subunit 6)
Description:
Component of the origin recognition complex (ORC) that binds origins of replication. DNA-binding is ATP-dependent. The specific DNA sequences that define origins of replication have not been identified yet. ORC is required to assemble the pre-replication complex necessary to initiate DNA replication. Does not bind histone H3 and H4 trimethylation marks H3K9me3, H3K27me3 and H4K20me3.
Synonyms: ORC6L
Tractability: Small molecule: a structure with a bound ligand is known. PROTAC: UniProt records ubiquitination sites on it; ubiquitination databases record sites on it.
Gene: Protein-coding gene on chromosome 16 (46,689,394 to 46,698,394, forward strand). Ensembl gene ENSG00000091651.
Subcellular location: Nucleus
Subcellular location (Human Protein Atlas): Nucleoli fibrillar center; Nucleoplasm
Pathways (Reactome):
DNA Replication: Activation of the pre-replicative complex; Assembly of the ORC complex at the origin of replication; Assembly of the pre-replicative complex; CDC6 association with the ORC:origin complex; Orc1 removal from chromatin
Cell Cycle: Activation of ATR in response to replication stress; E2F-enabled inhibition of pre-replication complex formation
Gene Ontology:
Molecular function: protein binding; DNA binding
Biological process: DNA replication initiation; DNA replication; DNA-templated DNA replication
Cellular component: fibrillar center; membrane; nuclear origin of replication recognition complex; nucleoplasm; origin recognition complex; cytosol; nucleus
Genetic constraint (gnomAD): Loss-of-function variants: 24 observed, 18.48 expected, observed/expected ratio (o/e) 1.3, 90% interval 0.94 to 1.78. The synonymous counts are far from expectation, so gnomAD's model fits this gene poorly and the ratio says little. Missense variants: 248 observed, 230.02 expected, observed/expected ratio (o/e) 1.08, 90% interval 0.97 to 1.2. Synonymous variants: 107 observed, 82.7 expected, observed/expected ratio (o/e) 1.29, 90% interval 1.11 to 1.52.
Gene-disease validity (ClinGen):
ClinGen rates the evidence that ORC6 causes each of these diseases.
Meier-Gorlin syndrome 3 (autosomal recessive): Definitive.
Homologues: Orthologues: chimpanzee ORC6 (99% identical), macaque ORC6 (96% identical), pig ORC6 (85% identical), rabbit ORC6 (84% identical), guinea pig ORC6 (82% identical), dog ORC6 (80% identical), mouse Orc6 (77% identical), rat Orc6 (74% identical), tropical clawed frog orc6 (60% identical), zebrafish orc6 (52% identical), Drosophila melanogaster Orc6 (26% identical).
Diseases named in the same sentence as ORC6 in open-access papers:
ORC6 is named in the same sentence as 41 diseases in open-access papers, as found by Europe PMC text mining. Sharing a sentence is not in itself a finding about the gene and the disease. The quoted sentences say what the papers report.
colon cancer (11 papers, 2008 to 2025). "Research has also shown that the expression of ORC6 in colon cancer tissues is high and associated with invasion depth." (PMID 33188157, 2020). "Our interest in Orc6 stemmed from our previous studies with a comprehensive genomics analysis revealed that Orc6 is associated with 5-FU associated resistance in human colon cancer cell lines." (PMID 19112505, 2008). "ORC6 provides an excellent biomarker for gastric adenocarcinoma, colon cancer, rectal cancer, and prostate cancer." (PMID 36205357, 2023). "Inhibiting ORC6 can enhance the sensitivity of 5‐fluorouracil and cisplatin in patients with colon cancer." (PMID 36205357, 2023). "ORC6 has been shown to enhance drug resistance in patients with colon cancer, especially resistance to 5‐fluorouracil and cisplatin." (PMID 36205357, 2023). "In human colon cancer, downregulation of ORC6 sensitizes colon cancer cells to both 5-FU and cisplatin treatment." (PMID 35711825, 2022). "Another research reports that depletion of ORC6 increases the sensitivity of colonic cancer cell line HCT116 to cisplatin." (PMID 34395415, 2021). "In this study, we provide experimental evidence that decreasing Orc6 expression by RNA interference can sensitize colon cancer cell lines to two of the major chemotherapeutic agents 5-FU and cisplatin treatment." (PMID 19112505, 2008). "The goal of this study was to investigate the molecular and cellular impact of Orc6 in colon cancer." (PMID 19112505, 2008). "We demonstrated that the down regulation of Orc6 sensitizes colon cancer cells to both 5-FU and cisplatin (cis-pt) treatment." (PMID 19112505, 2008). "Moreover, a reduction in ORC6 expression sensitizes human colon cancer cells to 5-fluorouracil and cisplatin." (PMID 33188157, 2020). "In addition, SNHG1 exhibited potentials in regulating the initiation and metastasis of colon cancer via cell cycle signaling pathway by working as a miR-484-mediated ceRNA of ORC6." (PMID 33194594, 2020). "Genes, such as ORC6 and GTSE1, are linked with drug resistance in various cancers, such as colon cancer and gastric cancer, but these genes may be liable for drug resistance in BRCA." (PMID 31311202, 2019). "Orc6 may be a potential novel target for future anti cancer therapeutic development in colon cancer." (PMID 19112505, 2008). "Moreover, they found that decreased ORC6 expression sensitized human colorectal cell lines to 5-fluorouracil and cisplatin, and thus, ORC6 may be a novel therapeutic target in colon cancer." (PMID 32194798, 2020).
colorectal cancer (9 papers, 2008 to 2023). A primary or metastatic malignant neoplasm that affects the colon or rectum. "In colorectal cancer tissues, ORC6 expression is markedly upregulated, associated with the invasion depth of the tumor and the survival time of the patients." (PMID 34395415, 2021). "Previous studies from our group have shown that the expression levels of Orc6 were highly elevated in colorectal cancer patient specimens and the induction of Orc6 was associated with 5-fluorouracil (5-FU) treatment." (PMID 19112505, 2008). "Reportedly, upregulated ORC6 expression is indicative of a poor clinical outcome in colorectal cancer patients." (PMID 34395415, 2021). "In colorectal cancer, the ORC6 expression is upregulated, while a lower ORC6 expression correlates with a favorable long-term cancer prognosis, indicating that ORC6 may act as an oncogene in the early stage but exert the suppressor effects in the advanced stage." (PMID 36978046, 2023). "In addition, ORC6 might be useful for diagnosis and prognosis of colorectal cancer." (PMID 33910638, 2021).
Meier-Gorlin syndrome (8 papers, 2012 to 2022). "Together, these results show that highly conserved amino acid residues in the C-terminal domain of Drosophila Orc6, including the tyrosine mutated in human Orc6 in Meier-Gorlin syndrome, mediate the recruitment of Orc6 into ORC." (PMID 24137536, 2013). "Together, our results suggest that Meier-Gorlin syndrome mutations in Orc6 impair the formation of ORC hexamers, interfering with appropriate ORC functions." (PMID 24137536, 2013). "Strikingly, a mutation found in patients with Meier-Gorlin syndrome maps to a highly-conserved C-terminal segment in Orc6, destabilizing the interaction of Drosophila and human Orc6 with both Orc3 alone and with the core Orc1–5 subcomplex." (PMID 24137536, 2013). "Mutations in three of the six ORC subunits, including Orc6, have been found in people with Meier-Gorlin syndrome." (PMID 24137536, 2013). "Although the overall function of Orc6 has remained somewhat debatable, the subunit is one of the pre-RC components recently shown to be mutated in patients with Meier-Gorlin syndrome (MGS)." (PMID 24137536, 2013). "Taken together, these results suggest that the MGS mutation in Orc6 directly affects the integrity of ORC, and indicate that destabilization of ORC contributes to the pathogenesis of Meier-Gorlin syndrome caused by mutations in Orc6, ultimately interfering with pre-RC assembly and origin licensing." (PMID 24137536, 2013). "Orc6 is one of several pre-RC components found mutated in Meier-Gorlin syndrome (MGS) patients." (PMID 24137536, 2013). "In humans, mutations in ORC1, ORC4, ORC6, CDT1, and CDC6 are detected in Meier-Gorlin syndrome (MGS) patients." (PMID 33522487, 2021). "A form of dwarfism known as Meier-Gorlin syndrome (MGS) is caused by recessive mutations in one of six different genes (ORC1, ORC4, ORC6, CDC6, CDT1, and MCM5)." (PMID 29036220, 2017). "Recently, mutations in genes encoding ORC1, ORC4, ORC6, CDT1, and CDC6 were identified in patients displaying Seckel syndrome (SS) and/or Meier-Gorlin syndrome (MGS)." (PMID 23516378, 2013). "Mutations in ORC1, ORC4, ORC6, CDT1, and CDC6, which encode proteins required for DNA replication origin licensing, cause Meier-Gorlin syndrome (MGS), a disorder conferring microcephaly, primordial dwarfism, underdeveloped ears, and skeletal abnormalities." (PMID 23516378, 2013). "Meier-Gorlin syndrome (MGS) is caused by mutations in components of the prereplication and pre-initiation DNA replication complexes (ORC1, ORC4, ORC6, CDT1, CDC6, GMNN, CDC45), which license replication origins and mediate loading and functioning of the replication fork helicase." (PMID 28630177, 2017). "Additionally, mutations in key components involved in initiation of DNA replication, such as ORC1, ORC4, ORC6, CDT1, CDT6, and CDC45, have been reported to be the cause of Meier-Gorlin syndrome, a primordial dwarfism syndrome." (PMID 28915237, 2017).
prostate carcinoma (7 papers, 2015 to 2025). A carcinoma that arises from epithelial cells of the prostate gland. "Of special note, our data, for the first time to the best of our knowledge, demonstrated that the ORC6 is associated to Treg cell infiltration in prostate cancer." (PMID 36978046, 2023). "In addition, miR-582-3p inhibition affects prostate cancer (PCa) cell function by silencing ORC6 expression, and overexpression of miR-582-3p accelerates smooth muscle cell proliferation and promotes carotid artery stenosis progression." (PMID 40597380, 2025). "A negative correlation was observed between the tumor endothelial cell infiltration and ORC6 expression in almost all tumors, whereas the immune infiltration of T regulatory cell was noted to be statistically positively correlated with the expression of ORC6 in prostate cancer tissues." (PMID 36978046, 2023). "Of note, ORC6, the smallest subunit of ORC, has been reported to be dysregulated in some types of cancers (including prostate cancer), however, its prognostic and immunological significances remain yet to be elucidated." (PMID 36978046, 2023). "Consistent with this line of evidence, we demonstrated that ORC6, DCD6, MCM7 together with PCNA and cyclin E were diminished in quiescent prostate cancer cells." (PMID 26416244, 2015).
breast carcinoma (6 papers, 2011 to 2022). "Few studies have focused on the gene function of ORC6 in breast cancer, but single-nucleotide polymorphisms (SNPs) were detected in this breast cancer-related gene." (PMID 31182966, 2019). "To clarify the clinical significance of SHCBP1 and ORC6, we carried out a survival prediction analysis of these genes using Affymetrix microarray expression profiles in 4934 breast cancer patients available in the Kaplan–Meier (K–M) plotter." (PMID 35886011, 2022). "Genes in the DNA replication initiation pathway including ORC6 were shown to have prognostic values for numerous cancers including breast cancer." (PMID 35886011, 2022). "Our study showed that ASPM, INHBA, NUF2, ORC6, UBE2T and PKMYT1 are associated with cell proliferation, and the expressions of these genes were also elevated in our breast cancer tissue transcriptome." (PMID 31182966, 2019). "For breast cancer we observed that rs3803662 is trans-acting on origin recognition complex subunit 6 (ORC6L)." (PMID 21829388, 2011). "Therefore, we suggest that SHCBP1 and ORC6 are prime targets for anti-cancer interventions in breast cancer treatment." (PMID 35886011, 2022). "We propose that SHCBP1 and ORC6 are novel oncogenes involved in breast cancer development." (PMID 35886011, 2022). "We hypothesized that the observed structural variation breakpoints in MCF7 cells, and observed over-expression of SHCBP1 and ORC6, affect the outcomes of breast cancer patients whose primary tumors are ER-positive." (PMID 35886011, 2022). "Importantly, two of the over-expressed genes, SHCBP1 and ORC6, in this cluster also show significantly increased expression in breast cancer tissues reported in TCGA." (PMID 35886011, 2022).
glioma (4 papers, 2023 to 2025). A benign or malignant brain and spinal cord tumor that arises from glial cells (astrocytes, oligodendrocytes, ependymal cells). "In the present study, we explored the expression patterns, biological functions, and underlying mechanisms of ORC6 in glioma." (PMID 38971772, 2024). "We here explored the expression patterns, biological functions, and underlying mechanisms associated with ORC6 (origin recognition complex 6) in glioma." (PMID 38971772, 2024). "High ORC6 expression was associated with poor prognosis in glioma patients." (PMID 38971772, 2024). "Thus, the potential mediation of TOP2A expression could represent another pivotal mechanism underlying ORC6-driven glioma cell growth." (PMID 38971772, 2024). "Such as lncRNA COX10-AS1 was significantly increased in glioma tissues and cell lines and promoted cell proliferation, migration and invasion by competitively binding miR-1-3p to regulate ORC6 expression." (PMID 39951205, 2025). "After removing missing prognosis data, samples were divided equally based on the median ORC6 expression level (151 ORC6-high and 150 ORC6-low), an elevation in ORC6 expression correlates with poor overall survival among glioma patients." (PMID 38971772, 2024). "The same lentiviral ORC6-expressing construct was employed to generate ORC6-overexpressing cells (“oeORC6”) in additional patient-derived primary human glioma cells (“P2/P3”) and immortalized A172 cells." (PMID 38971772, 2024). "Measurement of cytosolic Cytochrome C using an ELISA kit revealed an elevation following ORC6 silencing or KO in P1 glioma cells." (PMID 38971772, 2024). "The trypan blue staining assay results further indicated that ORC6 silencing or KO led to significant cell death in P1 glioma cells." (PMID 38971772, 2024). "Conversely, overexpression of ORC6 in primary human glioma cells led to an increase in TOP2A expression." (PMID 38971772, 2024). "In other primary glioma cells (P2/P3) and immortalized A172 cells, the application of shORC6-s1 for silencing ORC6 led to a similar increase in caspase-3 activity." (PMID 38971772, 2024). "After excluding samples with missing prognosis data (n = 3), TCGA glioma samples were categorized into two groups based on the median ORC6 expression level: 349 samples with high expression and 349 samples with low expression." (PMID 38971772, 2024). "By employing bioinformatics analyses, we uncovered a substantial elevation in ORC6 expression within human glioma, correlating with diminished overall survival and disease-free survival, high tumor grade, and wild-type IDH status." (PMID 38971772, 2024). "The results showed that RBPJ siRNA resulted in the most significant decrease in ORC6 mRNA expression within P1 glioma cells." (PMID 38971772, 2024). "Based on the result, it can be concluded that ORC6 represents a promising and new therapeutic oncotarget for human glioma." (PMID 38971772, 2024). "Examination of all 20 pairs of ORC6 protein expression data revealed a clear upregulation of ORC6 protein in glioma tissues (P < 0.001 vs. “N” tissues)." (PMID 38971772, 2024). "Silencing or KO of ORC6 reduced the mRNA and protein levels of these genes, while overexpression of ORC6 increased their expression in primary glioma cells." (PMID 38971772, 2024). "In vivo experiments demonstrated a significant reduction in the growth of patient-derived glioma xenografts in the mouse brain subsequent to ORC6 KO." (PMID 38971772, 2024). "Remarkably, oeRBPJ correspondingly led to an increase in ORC6 mRNA and protein expression in P1 glioma cells." (PMID 38971772, 2024). "We first conducted a comprehensive analysis from The Cancer Genome Atlas (TCGA) database to investigate the expression of ORC6 in glioma." (PMID 38971772, 2024). "The use of the same shORC6-s1 treatment along with puromycin selection led to a substantial reduction in ORC6 mRNA across these glioma cells, while the expression of ORC2 mRNA remained unaltered." (PMID 38971772, 2024).